ITK (IL2 inducible T cell kinase)
Diseases named in the same sentence as ITK in open-access papers (continued):
Sharing a sentence is not in itself a finding about the gene and the disease.
cancer (27 papers, 2014 to 2026). A tumor composed of atypical neoplastic, often pleomorphic cells that invade other tissues. "The fact that the most enriched processes associated with ITK’s first neighbors is T-cell activation suggests us the relevance that immune infiltration exerts on this carcinoma." (PMID 37693315, 2023). "In particular, we characterize global features of functional dynamics for members of the EGFR, CDK, NEK, BTK, and ITK kinases that have various cancer mutations." (PMID 24817905, 2014). "Soquelitinib (CPI-818) is an orally active and highly selective covalent ITK inhibitor and is a potential novel target to enhance the immunotherapy of cancer." (PMID 41567642, 2025). "We also analyzed the cytotoxic potential of ITK-KO CD19-CAR-T cells following repeated exposure to cancer cells." (PMID 39589809, 2024). "Regarding ITK gene expression, it is important to note its significant correlation with the prognosis in other cancer types." (PMID 37693315, 2023). "We also showed evidence that ITK’s expression is driven by methylation since its hypomethylation in cancer resulted in overexpression." (PMID 37693315, 2023). "Our findings provide evidence and a rationale for ITK inhibitors to be tested together with ICB for the treatment of patients with cancer that have been excluded from ICB immunotherapy." (PMID 37735204, 2023). "The promise of targeting ITK in cancer is bolstered by the growing success of targeting protein family member BTK, which plays a similar role in B cells and B cell tumors." (PMID 35911672, 2022). "Altogether, while additional studies are needed to clarify the impact of treating cancer with a combination of PD-1 blockade and ITK/BTK inhibitors, this possibility is mechanistically promising and clinically feasible with current approved drugs." (PMID 35911672, 2022). "According to our study, ITK presents dual function in the immune TME of HCC, and further exploration should be carried out to determine the interaction between ITK and other immune cells, as well as cancer cells." (PMID 34282055, 2021). "We also investigated the effect of ITK expression on cell proliferation using in vivo models in which immunodeficient mice were inoculated subcutaneously with cancer cells." (PMID 34283052, 2021). "This indicated that patients with low ITK expression were with poor prognosis, mainly because of the factors involved in the cancer development." (PMID 34702300, 2021). "ITK is associated with poor clinical outcome in TSCC, and data suggest that ITK enhances the proliferation of cancer cells in the malignant phenotype via activation of de novo purine biosynthesis through phosphorylation of GART." (PMID 34283052, 2021). "Our data also showed that ITK enhances the proliferation of cultured cancer cells." (PMID 34283052, 2021). "In addition, phosphoproteomic and metabolomic analyses were performed to investigate the mechanism of cancer cell proliferation via ITK and the de novo purine biosynthesis pathway via GART phosphorylation." (PMID 34283052, 2021). "We therefore investigated the role of ITK in epithelial malignant tumors." (PMID 34283052, 2021). "Notably, two trunk genes (SPEN and ITK), a branch gene (SMARCE1), and several private genes (FAT4, CACNA1D, ATR, RUNX1T1, TERT, and SRGAP3) were defined as cancer-associated genes, according to the cancer gene census." (PMID 28716121, 2017). "Nevertheless, this is the first report demonstrating that ITK is associated with poor clinical outcome in TSCC and that ITK might be involved in enhancing the proliferation of cancer cells in the malignant phenotype via activation of de novo purine biosynthesis through phosphorylation of GART." (PMID 34283052, 2021). "Interestingly, our panel included genes already described to be cancer predisposition genes (FAS, ITK, KIF1B, PGR and MET) or previously reported as playing important roles in cancer (ABI1, ARID5B, DNMT3A, HEY1, KDM5C, NCOA1, NUP98, and SLC34A2), or in DNA repair process (FANCF)." (PMID 30925779, 2019).
cancer (continued). "In conclusion, our study demonstrates that intermittent ITK inhibition can dampen TCR signaling thereby mitigating T cell exhaustion and augmenting ICB therapy in ICB-resistant cancers." (PMID 37735204, 2023). "The literature discussed here was obtained from a search of the published literature and ClinicalTrials.gov with the following key terms: checkpoint inhibition, cancer immunotherapy, PD-1, PD-L1, SHP2, PTPN2, ITK, VRK2, CDK4/6, GSK-3, and PAG." (PMID 35911672, 2022). "SHP2, ITK, VRK2, PTPN2, GSK-3, CDK4/6, and PAG all have evidence supporting their relationship to the PD-1 pathway in T cells and pro-tumorigenic role in cancer cells." (PMID 35911672, 2022). "Ibrutinib is a Bruton’s tyrosine kinase (BTK) and interleukin-2-inducible kinase (ITK) inhibitor used for treating chronic lymphocytic leukaemia (CLL) and other cancers." (PMID 32025027, 2020). "In contrast, immune-related kinases (ZAP70, SYK, ITK, and CSF1R) displayed reduced activity, implicating dampened immune signaling in pathways like PD-L1 Expression and PD-1 Checkpoint in Cancer (hsa05235), T Cell Receptor Signaling (hsa04660), and B Cell Receptor Signaling (WP23)." (PMID 41387887, 2025). "Compared to the derivatives we synthesized, ibrutinibexhibited significant cytotoxic activity against RAMOS cells (IC50 = 0.29 ± 0.04), in addition to its activity againstBTK-null and ITK-positive cancer cells and non-malignant fibroblastlines." (PMID 38405484, 2024). "Their results indicated the effectiveness of 1H-benzo(d)imidazol-2-amine-based inhibitor of interleukin-2-inducible T-cell kinase (ITK) (NCGC00188382, inhibitor #1) to inhibit growth and induce apoptosis in vitro and suppress cancer progression and metastasis in vivo." (PMID 33198323, 2020). "Since ITK is a SHP2-dependent specific mediator of PD-1 signaling, the combination of ITK inhibitors with PD-1 blockade may improve upon PD-1 monotherapy in the treatment of cancer." (PMID 35911672, 2022). "In experimental models using multiple cell lines, we found that the ITK inhibitor Cmpd-5 significantly diminished the proliferation of cancer cells enhanced by ITK expression; however, the ITK inhibitor had no adverse impact on the proliferation of mock control cells." (PMID 34283052, 2021).
infection (16 papers, 2011 to 2022). The state of being infected such as from the introduction of a foreign agent such as serum, vaccine, antigenic substance or organism. "Deficiencies in CD4, LCK, LAT and ITK have all been associated with immunodeficiency syndromes and an increased risk of childhood infections, highlighting their importance in determining infection risk." (PMID 35608955, 2022). "In contrast, HIV-1 particles that were pseudotyped with VSV-G were able to undergo membrane fusion and infection in ITK-deficient cells." (PMID 29453458, 2018). "We hypothesize that HIV with viral glycoproteins that weakly bind to receptors, e.g., HIV-1 Env BH10, need this additional attachment for infection of Jurkat cells and infection of ITK-deficient Jurkat cells may need viral glycoproteins that have a stronger interaction with receptors, e.g., VSV-G." (PMID 29453458, 2018). "PIK3R1, ITK and TMEM173 were identified as potential positional candidate genes associated with infection of Mycobacterium avium subspecies paratuberculosis in cattle." (PMID 32993537, 2020). "The most common adverse event in patients with CLL is infection (83%) that may be related to the inhibition of ITK in T cells and that of BTK in neutrophils and macrophages." (PMID 36138486, 2022). "With the Indirect approach, the ITK gene showed a remarkably significant increase in all infection." (PMID 32993565, 2020). "Given the potential for inhibition of ITK, patients being treated with Ibrutinib may need to be monitored for infection or potential reactivation of latent Mtb." (PMID 32038633, 2019). "Infection assays with HIV-1 enveloped particles (from clone L102, a variant of the C-terminally truncated (at amino acid 712) HIV-1 Env strain BH10) showed a strong dependency on ITK expression." (PMID 29453458, 2018). "Infections show the impact of ITK on T cell differentiation and T cell effector function." (PMID 29867957, 2018). "Our goal was to further explore the relevance of ITK for infection of HIV-1 and identify novel interaction partners that could be explored as targets to interfere with viral replication." (PMID 29453458, 2018). "Furthermore, ITK appears to regulate the dynamics of lung myeloid cells, which may further contribute to immune control of Mtb at the early stage of infection." (PMID 32038633, 2019). "The increased infection rate can be attributed to the impairment of innate and adaptive immunity by the BTKi via inhibition of BTK (on-target effect) and ITK (off-target effect) signalling pathways." (PMID 36138486, 2022). "Jurkat cells treated with the ITK inhibitor showed a concentration-dependent reduced susceptibility for HIV-1 transductions that were mediated by the HIV envelope protein, but infections were not repressed when VSV-G pseudotypes were tested." (PMID 29453458, 2018). "After infection, MP antigens stimulate and upregulate T cell surface molecules including CD3D, CD3E, CD3G, and CD8, followed by the upregulation of downstream molecules including CD3Z, FYN, LCK, ZAP70, GADS, P38, and ITK." (PMID 29967623, 2018). "To determine whether ITK is required for Tr1 cell development during these infections, we challenged mice with N. brasiliensis larvae or influenza A (WSN) virus, and found that ITK is required for Tr1 cell differentiation during parasitic and viral infections." (PMID 28635957, 2017). "However, since other kinases such as ITK, TEC, and BMX also harbour a corresponding residue in the ATP-binding site, a series of off-target effects, including bleeding, atrial fibrillation, and infection can, occur." (PMID 36138486, 2022).
hematological malignancies (4 papers, 2020 to 2026). "The penetrance of ITK deficiency for classical EBV-driven hematological disorders is, thus, incomplete, at least by the mid-20s, and it is crucial to consider infections other than EBV-related diseases, including TB, when confronted with patients with inherited ITK deficiency." (PMID 36326697, 2023). "We also analyzed a patient homozygous for the R29C variant, a well-characterized LOF mutant of ITK, who had EBV viremia in the absence of hematological disorders or a history of TB (P4)." (PMID 36326697, 2023).
inflammation (3 papers, 2019 to 2025). Aberrant reaction of the microcirculation characterized by movement of fluid and leukocytes from the blood into extravascular tissues. "To determine the role of ITK in SR-HP, we analyzed the development of lung inflammation following exposure to SR in WT and Itk−/− mice." (PMID 35210549, 2022). "The hosts' ability to limit bacterial growth and control pulmonary inflammation was, however, impaired in the absence of ITK." (PMID 32038633, 2019).
hematopoietic cancers (2 papers, 2021 to 2024). "In 3 independent studies, ZAP70, FYN, GRAP2, ITK, and CD247 (encoding CD3ζ) were highly upregulated in patients with T-ALL compared with individuals acting as healthy controls or people with other hematopoietic cancers, similar to our murine study." (PMID 38618957, 2024). "Furthermore, we found that expression levels of ZAP70, FYN, GRAP2, ITK, and LCK as well as two further TCR pathway kinases, PLCG1 and LAT, were highest in human T-ALL cell lines compared with other hematopoietic cancer lines." (PMID 38618957, 2024).
cardiovascular diseases (1 paper, 2025). "Nonetheless, given the close link between inflammation and cardiovascular diseases, it remains a prudent measure to monitor cardiovascular events in patients receiving long-term ITK inhibitor therapy." (PMID 41567642, 2025).
ITK also shares sentences with these, for which no sentence is quoted: autoimmune lymphoproliferative syndrome (3 papers); multiple sclerosis (3); bacterial infection (2); diabetes (2); dysgammaglobulinemia (2); lung carcinoma (2); neuroblastoma (2); systemic lupus erythematosus (2); acute myeloid leukemia (1); airway hyperresponsiveness (1); allergic contact dermatitis (1); Allergy (1); autism spectrum disorder (1); childhood asthma (1); chronic granulomatous disease (1); clear cell renal carcinoma (1); colon carcinoma (1); combined immunodeficiency (1); COVID-19 (1); diffuse large B-cell lymphoma (1); endocrine disorder (1); Ewing sarcoma (1); experimental autoimmune encephalomyelitis (1); gastritis (1); gastrointestinal stromal tumor (1); genetic disorders (1); Griscelli syndrome type 2 (1); hearing loss (1); helminthic infection (1); Hepatosplenomegaly (1).
A further 30 diseases each share a sentence with ITK in 1 paper.